MMP9 (matrix metallopeptidase 9)
Diseases named in the same sentence as MMP9 in open-access papers (continued):
Sharing a sentence is not in itself a finding about the gene and the disease.
breast carcinoma (continued). "Numerous tumor-derived cytokines including granulocyte macrophage colony-stimulating factor (GM-CSF), thymic stromal lymphopoietin (TSLP), matrix metalloproteinase 3 (MMP-3) and matrix metalloproteinase 9 (MMP-9) have been reported to contribute to breast cancer progression." (PMID 32887217, 2020). "DDR1 mediates MMP9 induced by native type IV collagen in MDA-MB-231 breast cancer cells." (PMID 32090682, 2020). "It is unclear whether an 8-week HIIT intervention influences MMP-9 in breast cancer patients undergoing anthracycline chemotherapy." (PMID 32246106, 2020). "LBDE has been reported to suppress breast cancer metastases and bone microenvironment by inhibiting the parathyroid hormone-related protein (PTHrP), matrix metallopeptidase 9 (MMP-9) and cathepsin K activities in breast cancer cells and osteoclastic bone resorption." (PMID 32046692, 2020). "Similarly, inhibition of Wnt/β-catenin signaling or expression of its downstream target MMP-9, results in decreased cell proliferation and metastasis in breast cancer and hepatocellular carcinoma." (PMID 33264103, 2020). "Furthermore, our previous investigation has indicated that rCTII can robustly decrease MMP-3 and MMP-9 expression in breast cancer." (PMID 33167431, 2020). "In addition, we observed that IL-22 promoted the invasive activity of breast cancer cells by inducing MMP-9 to facilitate the accumulation of macrophages, thereby providing an initial signal for cancer metastasis." (PMID 31935914, 2020). "Tomatine, which is a secondary metabolite from tomato, suppresses MMP-2 and MMP-9 activities and cell proliferation in breast cancer MCF-7 cell line and structure-activity relationships of α-, β1-, γ-, and δ-tomatine and tomatidine against various cancer cells have been studied." (PMID 31941156, 2020). "Next, the role of IL-22R1, S1PR1, and MMP-9 in breast cancer progression and the potential prognostic value of assaying these factors were evaluated through the immunohistological staining of adjacent normal, invasive breast carcinoma, and metastatic breast carcinoma tissues." (PMID 31935914, 2020). "Similarly, MMP-9 overexpression is higher in high-grade and more invasive breast cancers (such as triple negative and Her2-positive), where it is associated with metastasis and relapse." (PMID 32984031, 2020). "Extracts obtained from fermented sprouts at IC0 dosages were able to inhibit migration of breast cancer cells through their influence on intracellular ROS generation; membrane stiffening; adhesion; regulation of MMP-9, N-cadherin and E-cadherin at transcriptional level; or VEGF secretion." (PMID 31963833, 2020). "High levels of MMP-9 in serum in breast cancer patients were also correlated with poor outcomes." (PMID 32466129, 2020). "Indeed, we also found that the levels of MMP-2 and MMP-9 in oral cancer cells or breast cancer cells are higher than in human gingival fibroblasts under the stimulation of PM." (PMID 32922544, 2020). "Moreover, cytokines, such as IL-17 and TNF-a, activate transcription of LCN2, and stroma-derived LCN2 enhances the malignant phenotype of breast cancer cells and promotes cell metastasis, possibly by interacting with MMP-9." (PMID 32575507, 2020). "Our findings thus indicated that elevated IL-22R1, S1PR1, and MMP-9 expression may result in poorer survival in cases of relapsed breast cancer." (PMID 31935914, 2020). "MMP9 was shown to be differentially expressed within different molecular subtypes of breast cancer." (PMID 33066411, 2020). "In addition, pKAL inhibited expressions of the proteins (CD44, Oct 3/4, β-catenin and MMP-9) that are assumed to be related to the RT resistance of RT-R-MDA-MB-231 human breast cancer cells." (PMID 32326231, 2020). "This cell has been known to express MMP9 during breast cancer." (PMID 33066411, 2020). "Daucosterol linoleate suppresses VEGF, MMP2, and MMP9 expression in breast cancer." (PMID 33426081, 2020).
breast carcinoma (continued). "MMP-9, a protease, facilitates cancer cells in degrading extracellular matrix for metastasis and invasion, has been found to be overexpressed in many cancers, including breast cancer." (PMID 33013272, 2020). "In addition, a high activity of MMP-2 and MMP-9 has been observed in the serum and tissues of patients with breast cancer compared to healthy individuals." (PMID 31554180, 2019). "Moreover, MMP9 was a direct target of Osx and mediated the Osx-driven invasion potential of breast cancer cells." (PMID 30631043, 2019). "Targeting MTA2 with a short hairpin RNA could reduce cell proliferation and inhibit metastasis by downregulating MMP-2 or MMP-9 expression in breast cancer and glioma cells." (PMID 31771219, 2019). "The matrix remodeling protease gelatinase-B (Mmp9) is associated with breast cancer risk, and Mmp9, but not Mmp3, was elevated in glands from R72 mice." (PMID 30651598, 2019). "In breast cancer (BC), the addition of MMP-9 to cell lines resulted in a significant rise in HER2 expression, indicating that some MMPs may serve as regulators of HER2 expression on human epithelial cells." (PMID 31443252, 2019). "For instance, MMP-9 expression can be significantly reduced via the suppression of NF-κB as demonstrated in breast cancer cells following the application of the isothiocyanate Sulforaphane and in monocytic THP-1 cells treated with the labdane diterpenoid Andrographolide." (PMID 30935029, 2019). "In this study, we found that STAT3 could also mediate IL-6-induced MMP2 and MMP9 expression and breast cancer cell migration." (PMID 31409371, 2019). "The overexpression of MMP9 has previously been demonstrated in breast cancer." (PMID 30041514, 2019). "Interestingly, while MMP-9 has a suggested link to malignant progression and metastasis of TNBC and histological breast cancer grades, inflammation induced by MMP-9 can enhance tumor regression of experimental breast cancer." (PMID 31921385, 2019). "Among MMPs, MMP-9 expression is related to metastatization in many tumors, including breast cancer." (PMID 31540249, 2019). "Indeed, they showed that the functional cooperation of the Stat3 and AP-1 transcription factors is required for the transcription of MMP-9 gene in breast cancer cells." (PMID 31456939, 2019). "The MMP-9 expression varies according to the molecular subtypes of breast cancer." (PMID 31921385, 2019). "Moreover, studies have shown that cytoplasmic polyadenylation element binding protein 1 (CPEB1) inhibits breast cancer metastasis by reducing the expression of matrix metallopeptidase 9 (MMP9) mRNA." (PMID 31514467, 2019). "Moreover, MMP9 was a target of Osx and mediated the Osx-driven invasion capacity of breast cancer cells." (PMID 30631043, 2019). "Furthermore, western blotting analysis showed that knockdown of RAI14 inhibits the expression of MMP2 and MMP9 in breast cancer cells." (PMID 31772666, 2019). "While luteolin glycosides target the ER-mediated signaling pathway in ER (+) MCF-7 cells, these compounds might not inhibit migration and invasion signaling pathways mediated via MMP-9 in MDA-MB-231 TNBC breast cancer cells." (PMID 31611756, 2019). "In mice containing cells transfected with MMP, the metastatic ability of cancer cells was significantly enhanced, indicating that MMP-2 and MMP-9 may promote invasion and metastasis of breast cancer." (PMID 31514467, 2019). "Moreover, a higher expression of MMPs was associated with a poorer prognosis in breast cancer patients, with MMP-2 and MMP-9 being the major enzymes involved in this process." (PMID 31514467, 2019). "Moreover, RT-PCR results showed that RSF EtOAc significantly downregulated MMP-2 and MMP-9 expression, which play an important role in breast cancer metastasis." (PMID 31683960, 2019). "Furthermore, in the current study, the anti-invasive effect of compound B on breast cancer cells was verified by determining MMP-9 expression." (PMID 31387647, 2019).
breast carcinoma (continued). "All these results indicate MMP-9 as a potential biomarker for breast cancer patients." (PMID 31010242, 2019). "Based on the in vivo results, immunohistochemistry analysis further revealed that MMP-2 and MMP-9 expressions were reduced in the lung colonization lesions after BA treatment, implying that BA might diminish the aggressiveness of breast cancer cells in vivo." (PMID 31531187, 2019). "Downregulation of MMP-2 and MMP-9 expression induced by MPPa-PDT may enhance the therapeutic efficacy for breast cancer by restricting metastasis by upregulating cell apoptosis and necrosis." (PMID 31783821, 2019). "However, accumulating evidences suggested the famous downstream target genes of β-catenin including c-myc and MMP9 were remarkably correlated with breast cancer distant metastasis and poor prognosis." (PMID 31285694, 2019). "MMP-9 and TIMP-1 have been linked to the prognosis of breast cancer." (PMID 31514476, 2019). "In our study, we identified the promoting effect of BMAL1 on MMP9 transcription, which may provide a novel mechanism for human breast cancer invasion and metastasis." (PMID 31346317, 2019). "Moreover, MMP9 was a direct target of Osx and mediated the Osx-driven invasion of breast cancer cells." (PMID 30631043, 2019). "We hypothesize that in malignant breast cancers, more MMP‐9 are expressed, which leads to more releases of TGF‐β from its latent form." (PMID 31264317, 2019). "Thus, due to the paucity of studies in the literature, further studies with a larger sample size are necessary to improve knowledge of the role of MMP-2 and MMP-9 in the progression and prognosis of breast cancer." (PMID 31839881, 2019). "On the other hand, the majority of studies in literature have investigated serum concentrations of MMP-2 and MMP-9 and showed a higher concentration of these serum proteins in breast cancer patients than in women with fibroadenoma, corroborating data of immunohistochemical expression." (PMID 31839881, 2019). "One may assume that the activated TGF‐β/SMAD signalling induced by overexpression of MMP‐9 may also promote the progression and probably metastasis of canine breast cancers." (PMID 31264317, 2019). "Next, to test whether carnosol inhibits breast cancer cell invasion by affecting the expression of MMP-9, we examined the expression level of MMP-9 in the conditioned media." (PMID 31456939, 2019). "Matrix metalloproteinase 9 (MMP‐9) has been frequently noticed in the breast cancers." (PMID 31264317, 2019). "Low expression levels of MMP-2 and MMP-9 in breast cancer patients may indicate a relatively good patient prognosis." (PMID 30518369, 2018). "Moreover, it has been reported that AFU was able to decrease the activity of MMP-9, therefore diminishing the invasive capability of breast cancer." (PMID 29682557, 2018). "(A-C) Boxplot representation of IL-6 (A) (Student’s t test, P < 2.2 × 10− 16), CCL2 (B) (Student’s t test, P < 2.2 × 10− 16), and MMP9 (C) (Student’s t test, P < 2.2 × 10− 16) expression levels in ER+/PR+ breast cancer compared to triple-negative breast cancer (TNBC)." (PMID 30458886, 2018). "Many studies have explored the value of MMP-9 as a biomarker for breast cancer." (PMID 30262739, 2018). "Such evidence for a cross-talk between IL-17A and MMP-9 suggest that their simultaneously targeting can be highly beneficial for inhibiting tumor progression in various types of cancer, including breast cancer, gastric cancer, cervical cancer, hepatocellular carcinoma, and lung cancer." (PMID 29983876, 2018). "In addition, IL-17A stimulates the expression of the MMP-9 mRNA, and IL-17A-dependent invasion of breast cancer cells can be inhibited by MMP-9 inhibitors." (PMID 29983876, 2018). "The aims of this study were to objectively determine the in situ expression and significance of TAM biomarkers (CD68, CD163, and MMP-9) in breast cancer and to identify subclasses of patients who could benefit from TAM-targeting therapies." (PMID 30558648, 2018).
breast carcinoma (continued). "Some other study noted that MMP-9 could be regulated by DNA methylation in breast cancer, which might resulted in the first step of metastasis through extracellular matrix degradation." (PMID 30241470, 2018). "In other words, interaction of Plac1 and Furin may be sufficient to alter this pathway, further enhancing MMP2 and MMP9 protein levels to promote the invasion and metastasis of breast cancer cells." (PMID 29704427, 2018). "MMP-9 promotes cell invasion downstream of ERK in breast cancer cells." (PMID 30046386, 2018). "Using active MMP-9 activity levels in serum and RhoA expression patterns in circulating leucocytes, the authors developed a non-invasive multiparametric approach to stratify patients with breast cancer." (PMID 30262739, 2018). "So far, indirect evidence allows to speculate that metalloprotease (MMP9) and macrophage colony-stimulating factor (M-CSF) levels in breast cancer cells (MDA-MB-231) correlate with TAM infiltration and OsteoMac polarization." (PMID 29760166, 2018). "Inhibiting any of a dozen different oncogenic pathway components, including EGFR, PI3K and MMP-9, could revert breast cancer cells." (PMID 29560860, 2018). "Other investigators have demonstrated that a constitutively active mutant form of STAT3 expressed in immortalized human mammary epithelial cells induces expression of MMP9 mRNA and protein and furthermore that MMP9 expression correlates with nuclear pSTAT3 expression in breast cancer tissues." (PMID 29875329, 2018). "In this context, the increase in THBS1 expression has been found to be associated with the enhancement of angiogenic properties in the gastric carcinoma model and more importantly, it has been reported to up-regulate the expression of MMP9 in breast cancer cells." (PMID 29748481, 2018). "It found a significant increase in MMP-9 expression in breast cancer cells." (PMID 30262739, 2018). "In vitro evidence from MCF7 breast cancer cells suggests that this may, in part, be due to, IL-1B-regulating breast cancer cell invasion by stimulating production of MMP-9 via focal adhesion kinase 1 FAK and the proto-oncogene tyrosine-protein kinase Src." (PMID 29760166, 2018). "(A) Regression of MMP-9+/CD68+ QIF scores in breast cancer TMA." (PMID 30558648, 2018). "The present study aimed to assess whether MMP-9 levels could predict patient survival and to analyse its prognostic value in comparison with the Molecular Taxonomy of Breast Cancer International Consortium (METABRIC) database." (PMID 30142200, 2018). "In addition, breast carcinoma cells produce MMP9 and TAFs enhance expression of MMP9 by tumor cells in the breast TME." (PMID 29921235, 2018). "The main results of this study suggest that the T allele and the TT genotype of 1562 C/T (rs 3918242) of the MMP-9 do not play a key role in breast cancer development." (PMID 30352460, 2018). "Additionally, casticin attenuated lung metastasis of mouse 4T1 breast cancer cells in the mice and down-regulated MMP-9 expression in the lung tissues of mice treated by casticin." (PMID 30401729, 2018). "In addition, MMP-9 was significantly associated with the levels of ER, PR, and HER2, which are important factors in breast cancer treatment." (PMID 30142200, 2018). "Our findings, identified ER+ tumors with high levels of MMP-9/CD163 co-expression as the potential target breast cancer group that could benefit from an MMP-9 targeting modality." (PMID 30558648, 2018). "The results showed that this stratification approach using MMP-9/RhoA biomarker-combination might be useful for early breast cancer diagnostics, although the authors admitted the existence of limitations in the stratification system." (PMID 30262739, 2018).
breast carcinoma (continued). "Surfactin can suppress the proliferation of the human colon carcinoma cell line LoVo, suppress TPA-induced breast cancer cell invasion through the inhibition of MMP-9 expression, and kill the human breast carcinoma cell line MCF-7 through a ROS/JNK-mediated mitochondrial/caspase pathway." (PMID 29777449, 2018). "A recent study showed that AFU decreased the invasion of human breast cancer cells by downregulating MMP-9, which may partially explain the correlation between lower levels of AFU and poor prognosis in breast cancer." (PMID 29682557, 2018). "Additionally, the study found that MMP-9 was differentially expressed within different molecular subtypes of breast cancer." (PMID 30262739, 2018). "Interestingly, our results revealed that high MMP-9 expression is associated with a high histological grade and HER2 subtype, as well as worse DFS and OS in patients with breast cancer." (PMID 30142200, 2018). "Additionally, morphine has been shown to inhibit expression and secretion of MMP-2 and MMP-9 in breast cancer cells in a time-dependent and concentration-dependent manner." (PMID 29347949, 2018). "Serum levels of MMP-9 were found to be high in breast cancer patients compared to healthy subjects." (PMID 30046386, 2018). "In another study, flavopiridol inhibited the secretion of MMP-2 and MMP-9 in mammary cancer cells." (PMID 30092754, 2018). "VEGF can act directly on T lymphocytes and elevated VEGF levels may contribute to the aberrant MMP-9 secretion by mammary tumour bearing T cells." (PMID 30517191, 2018). "TGF-β-induced expression of MMP9 in breast cancer cells requires TGF-β-activated kinase 1 (TAK1)." (PMID 28423685, 2017). "Furthermore, we showed that silencing of TOPK abrogated LPS-induced MMP9 promoter-driven transcriptional activity as well as MMP9 protein level, resulting in suppression of breast cancer cell migration or invasion in LPS/TLR4 signaling." (PMID 28212583, 2017). "It appears that elevation of TLR4 expression by TOPK in LPS response might occur via NF-kB or MMP9-mediated positive feedback loop leading to breast cancer invasion and metastasis, suggesting a possible mechanism regarding TOPK-mediated regulation of TLR4." (PMID 28212583, 2017). "Taken together, results demonstrated that MMP9 plays a key role in breast cancer cell migration, and that both of TOPK kinase activity and TOPK expression are required for LPS-induced MCF7 cell migration, suggesting the role of TOPK in regulation of MMP9 expression through NF-kB." (PMID 28212583, 2017). "Indeed, the MMPs are a major group of enzymes that regulate cell-matrix composition, and in particular MMP-9 is involved in angiogenesis as well as tumor growth, invasion and metastasis of various tumors, including breast cancer." (PMID 29202842, 2017). "In addition, overexpression of HO1 inhibited proliferation and invasion via down-regulation of MMP9 in pancreatic and breast cancer cells." (PMID 28679437, 2017). "Overexpression of MMP9 in breast cancer has been shown to promote invasion and metastasis." (PMID 28490334, 2017). "Finally, we find that TBC1D3 promotes the expression and activation of MMP-9 and the migration of human breast cancer cells, and interaction with CaM considerably enhances such effect of TBC1D3." (PMID 28422741, 2017). "Also, it has been suggested that VEGF and MMP-9 are critical cytokines for breast cancer cell invasion or metastasis, and that autocrine secretion of these cytokines by cancer cells importantly influences cancer cell behavior such as invasion." (PMID 28212583, 2017). "Further analysis is necessary to examine whether A77636′s action on Rac1 GTPase and/or RhoA GTPase may regulate matrix metalloproteinases such as MMP2 and MMP9 that may drive migration of breast cancer cells." (PMID 28374823, 2017). "TOPK-mediated regulation of NF-κB activity and MMP9 expression in LPS/TLR4 signaling might be a mechanistic link connecting inflammation to breast cancer malignancy." (PMID 28212583, 2017).